TECPR1 (tectonin beta-propeller repeat containing 1)
Description:
Tethering factor involved in autophagy. Involved in autophagosome maturation by promoting the autophagosome fusion with lysosomes: acts by associating with both the ATG5-ATG12 conjugate and phosphatidylinositol-3-phosphate (PtdIns(3)P) present at the surface of autophagosomes. Also involved in selective autophagy against bacterial pathogens, by being required for phagophore/preautophagosomal structure biogenesis and maturation.
Synonyms: KIAA1358; DKFZP434B0335; FLJ23419; FLJ90593
Tractability: PROTAC: ubiquitination databases record sites on it; its protein half-life has been measured.
Gene: Protein-coding gene on chromosome 7 (98,214,624 to 98,252,235, reverse strand). Ensembl gene ENSG00000205356.
Subcellular location: Cytoplasmic vesicle, autophagosome membrane; Lysosome membrane
Subcellular location (Human Protein Atlas): Vesicles
Gene Ontology:
Molecular function: phosphatidylinositol-3-phosphate binding; protein binding
Biological process: autophagosome maturation; autophagy; macroautophagy; regulation of autophagosome maturation
Cellular component: autophagosome membrane; early endosome membrane; lysosomal membrane; protein-containing complex; bounding membrane of organelle; cytoplasm; membrane
Genetic constraint (gnomAD): Loss-of-function variants: 122 observed, 134.99 expected, observed/expected ratio (o/e) 0.9, 90% interval 0.78 to 1.05. The upper end of that interval is the gene's LOEUF score, 1.05, which puts it in group 4 of 6, group 1 being the genes least tolerant of losing a copy. Missense variants: 1,432 observed, 1,476.1 expected, observed/expected ratio (o/e) 0.97, 90% interval 0.93 to 1.01. Synonymous variants: 642 observed, 609.11 expected, observed/expected ratio (o/e) 1.05, 90% interval 0.99 to 1.12.
Homologues: Orthologues: chimpanzee TECPR1 (99% identical), macaque TECPR1 (97% identical), rat Tecpr1 (87% identical), mouse Tecpr1 (87% identical), guinea pig TECPR1 (86% identical), rabbit TECPR1 (84% identical), pig TECPR1 (84% identical), dog TECPR1 (80% identical), tropical clawed frog tecpr1 (69% identical), zebrafish tecpr1b (51% identical), Drosophila melanogaster Pex23 (36% identical), zebrafish tecpr1a (25% identical).
Diseases named in the same sentence as TECPR1 in open-access papers:
TECPR1 is named in the same sentence as 11 diseases in open-access papers, as found by Europe PMC text mining. Sharing a sentence is not in itself a finding about the gene and the disease. The quoted sentences say what the papers report.
amyotrophic lateral sclerosis (1 paper, 2020). Amyotrophic lateral sclerosis (ALS) is a neurodegenerative disease characterized by progressive muscular paralysis reflecting degeneration of motor neurons in the primary motor cortex, corticospinal tracts, brainstem and spinal cord. "Furthermore, TECPR1 expression is downregulated in neurons of patients suffering from TDP-43 proteinopathies including amyotrophic lateral sclerosis and frontotemporal dementia." (PMID 32532970, 2020). "Interestingly, an accumulation of TDP-43 aggregates in frontotemporal dementia and amyotrophic lateral sclerosis correlates with a significant downregulation of TECPR1 expression in neurons." (PMID 32532970, 2020).
cognitive disorder (1 paper, 2025). A disease affects cognitive processes. "Lastly, CQ or 3‐MA treatment reversed TECPR1 induced improvement effects on autophagic and cognitive disorders, further proved that, TECPR1 activated the early and late process of autophagy to ameliorate the cognition of P301S‐tau mice." (PMID 39511758, 2025). "In summary, we found that P301S‐tau downregulated TECPR1 protein levels, leading to autophagy dysfunction by activating the mTOR signaling pathway, and exacerbating tau accumulation, ultimately resulting in synaptic plasticity impairments and cognitive deficits." (PMID 39511758, 2025).
non-small cell lung carcinoma (1 paper, 2025). A group of at least three distinct histological types of lung cancer, including non-small cell squamous cell carcinoma, adenocarcinoma, and large cell carcinoma. "TECPR1, identified in the carcinoma group, is associated with downregulating autophagy-related gene 5 (ATG5) when expressed at low levels in non-small cell lung cancer, suppressing autophagy and enhancing cell viability." (PMID 40446009, 2025).
tauopathies (1 paper, 2025). "P301S‐tau induced autophagic defects in the early and late process by inhibiting the expression of TECPR1, which enrich the autophagy research in tauopathies." (PMID 39511758, 2025). "However, the role of TECPR1 in tauopathy has not been reported yet." (PMID 39511758, 2025).
cancer (2 papers, 2025). A tumor composed of atypical neoplastic, often pleomorphic cells that invade other tissues. "First, in terms of immune function, variations related to the nuclear factor kappa B (NF-κB) signaling pathway (NLRP12, TNIP2, IRAK4) and the autophagy process (TECPR1, ATG2A, SOGA1, TOM1) were identified in both carcinoma and sarcoma tumor groups." (PMID 40446009, 2025). "Additionally, genes such as TSC2, FAM134C, USP36, TECPR1, and LRSAM1 are involved in pathways including macroautophagy and selective autophagy, which can contribute to cancer when dysregulated." (PMID 40279344, 2025).
neurodegenerative disease (1 paper, 2020). A disorder of the central nervous system characterized by gradual and progressive loss of neural tissue and neurologic function. "The neuroprotective function of TECPR1 that we discovered in our study implies that its augmented expression could potentially counteract the onset of neurodegenerative diseases." (PMID 32532970, 2020).
TECPR1 also shares sentences with these, for which no sentence is quoted: COVID-19 (1 paper); frontotemporal dementia (1); Kawasaki disease (1); memory (1); virus infection (1).